APC (APC regulator of Wnt signaling pathway)
Diseases named in the same sentence as APC in open-access papers (continued):
Sharing a sentence is not in itself a finding about the gene and the disease.
colorectal cancer (continued). "In fact, abnormal regulation of the APC/β-catenin pathway has been linked to 60–80% of sporadic colorectal cancers." (PMID 22363759, 2012). "Mutations of two key proteins in the pathway, APC and β-catenin, have been implicated in a range of cancers, including colorectal cancer." (PMID 22363759, 2012). "APC mutations occur in a high proportion of sporadic colorectal carcinomas (up to 80%) and were first identified in the germline of FAP (familial adenomatous polyposis) patients." (PMID 22509309, 2012). "The APC tumor suppressor gene is frequently mutated in human colorectal cancer, with nonsense mutations accounting for 30% of all mutations in this gene." (PMID 21909382, 2011). "Colorectal cancer cell line HCT-15 is activated for Wnt signaling by an APC truncating mutation, and signaling is partially inhibited by tankyrase RNAi." (PMID 21799911, 2011). "We evaluated readthrough efficiency for 11 nonsense mutations involved in colorectal cancer, with a view to identifying the nonsense mutations in the APC gene the most responsive to readthrough-inducing treatments." (PMID 21909382, 2011). "In particular, its role as a tumour suppressor protein whose loss of function leads to the development of colorectal cancer has attracted much attention, eventually identifying a pivotal role for APC in the WNT signalling pathway." (PMID 22216133, 2011). "Lastly, in the colorectal cancer cell line SW480 that also possesses a truncating APC mutation, tankyrase RNAi stabilizes AXIN1, AXIN2, and RNF146 proteins." (PMID 21799911, 2011). "In colorectal cancer and other tumor types, APC inactivation is frequently associated with nuclear and cytosolic accumulation of β-catenin as a measure of canonical Wnt pathway activation." (PMID 22216254, 2011). "LGR5 is a wnt target gene, and the wnt pathway is activated early in the progression of the majority of colorectal cancers through truncations of APC (Adenomatous Polyposis Coli) and, less frequently, mutations of β-catenin." (PMID 21829496, 2011). "Since it was first linked with colorectal cancer in 1991 the adenomatous polyposis coli protein (APC) has been extensively investigated." (PMID 22216133, 2011). "The APC gene is mutated in 80% of colon cancers and mutations occur early in the development of most polyploid colorectal cancers." (PMID 21909382, 2011). "Wnt signaling can become deregulated through multiple mechanisms to produce cancer or other diseases, particularly colorectal cancer for which APC or β-catenin is mutated in approximately 95% of tumors." (PMID 21799911, 2011). "In colorectal cancer, mutations of β-catenin, APC, and Axin increase the stability of β-catenin, leading to the overexpression of downstream targets and promoting cell proliferation and regulate cell differentiation." (PMID 22016777, 2011). "The APC mutations typically found in colorectal cancers result in the loss of both the MT and the EB1 interaction domains of the protein." (PMID 22216133, 2011). "In human cancer, overexpression of LGR5 has been noted in up to 90% of hepatocellular carcinomas with β-catenin mutations and in a large proportion of colorectal carcinomas, where APC mutations and hence dysregulated wnt signalling are preponderant." (PMID 21829496, 2011). "Recent studies aimed at comprehensive sequencing of genes mutated in colorectal cancer confirmed that APC and KRAS mutations are among the most common mutations found in colorectal cancer." (PMID 20298593, 2010).
colorectal cancer (continued). "In the development of esophageal cancer, dysfunction of Wnt/β-catenin signaling has been implicated, however, in contrast to colorectal cancer, mutation in adenomatous polyposis coli (APC) or β-catenin gene is a rare event in esophageal cancer." (PMID 20140245, 2010). "In colorectal cancers and several other tumors, loss of control of intracellular β-catenin levels through mutation to either β-catenin or APC result in stabilization of β-catenin and accumulation of the protein in the cytoplasm." (PMID 20140245, 2010). "For example, familial adenomatous polyposis (FAP) is characterized by heterozygous germline APC mutations, and APC somatic mutations are present in most sporadic colorectal cancers." (PMID 20051132, 2010). "In colorectal cancer, mutations in APC are found in 61% of patients and result in abnormal upregulation of β-catenin-dependent transcription." (PMID 19238201, 2009). "For example, we have found that several colorectal cancer cell lines with APC mutations show more nuclear accumulation of β-catenin when treated with LPA (unpublished data), which is consistent with previous reports." (PMID 19238201, 2009). "Mutation in APC is also the responsible initiating genetic event in the colorectal cancer syndrome familial adenomatous polyposis." (PMID 19238201, 2009). "This particular route accounts for a subset: only about half of colorectal cancer patients have detectable mutations in the APC gene, and alternative routes have been identified that do not involve APC." (PMID 19774079, 2009). "In sharp contrast with these observations, in colorectal cancer cells (APC-mutated), used as a positive control, we detected strong nuclear accumulation of β-catenin by the same technique." (PMID 19849855, 2009). "Inactivating mutations of APC gene in colorectal cancer and AXIN1 in HCC also activate canonical Wnt signaling by the same mechanism." (PMID 19849855, 2009). "APC mutations are found in over 80% of all colorectal cancers and have been assessed for screening and prognosis purposes in the clinical setting." (PMID 19845967, 2009). "Although mitotic recombination is the foremost mechanism of loss of heterozygosity in colorectal tumours, some colorectal carcinomas acquire deletions or gains of 5q around APC as an additional, later event during tumorigenesis." (PMID 19515250, 2009). "We found that BCL9 is required for efficient β-catenin-mediated transcription in Wnt-stimulated HEK 293 cells, and in the SW480 colorectal cancer cell line whose Wnt pathway is active due to APC mutation." (PMID 18627596, 2008). "Most cases of colorectal cancer are initiated by hyperactivation of the Wnt/β-catenin pathway due to mutations in the APC tumour suppressor, or in β-catenin itself." (PMID 18627596, 2008). "Overexpression of c-MYC also constitutes an early event after loss of the APC tumor suppressor gene that initiates colorectal cancer." (PMID 18190704, 2008). "Acquisition of truncating mutations in the adenomatous polyposis coli (APC) protein underlies the progression of the majority of sporadic and familial colorectal cancers." (PMID 17595655, 2007). "According to the paradigm for colorectal cancer development, mutations in the APC and K-ras are thought to contribute to the early developmental stages of colorectal cancer." (PMID 16356174, 2005). "Somatic mutations in APC are common in colorectal cancer and, similar to what has been seen by others, almost half of the tumors displaying APC mutations in our study were also methylated." (PMID 15476557, 2004).
colorectal cancer (continued). "For example, mutations in APC seem to play a particularly important role in colorectal cancer; is the peculiar sensitivity to APC mutations in the colonic epithelium understandable in terms of how the pathway performs in that tissue?" (PMID 14551908, 2003). "β-catenin is known to accumulate in the cytoplasm and nucleus of colorectal cancer cells through mutations in APC or β-catenin itself, and thereby function as a transcriptional activator when complexed with members of the Tcf family of DNA-binding proteins." (PMID 12439718, 2002). "Although many in vitro studies using cell lines have proven that mutations in the APC tumour suppressor gene occurs in most colorectal cancer and leads to the activation of β-catenin, this probably is not always the case in vivo." (PMID 11953860, 2002). "When APC is mutated, which occurs in up to 80% of colorectal cancer, β-catenin accumulates and translocates to the nucleus, where it binds the transcription factors of the TCF/LEF gene family and activates the expression of target genes." (PMID 11953860, 2002). "The I1307K polymorphism in APC has been found to predispose to colorectal cancer in Ashkenazi Jews, and has recently been associated with an increased risk for breast cancer in the same population." (PMID 10555757, 1999). "Chemically induced degradation of TNKS overcomes this limitation by stabilizing AXIN without puncta formation, providing a deeper suppression of the WNT/β-catenin pathway activity and the proliferation of colorectal cancer cells harboring dysfunctional APC mutations." (PMID 41040241, 2025). "APC loss-of-function mutations are common occurrences in colorectal cancer." (PMID 40141210, 2025). "Mutations in APC are also commonly found in sporadic colorectal cancers." (PMID 40624028, 2025). "For example, in colorectal cancer, sepsis-induced ROS has been shown to promote mutations in the APC gene, a key regulator of the Wnt signaling pathway, enhancing tumor progression by disrupting normal cellular processes and promoting uncontrolled cell proliferation." (PMID 40563999, 2025). "Notably, dysregulation of the Wnt/β-catenin pathway in colorectal cancer is often due to inactivating mutations of the APC tumor suppressor or oncogenic mutations of β-catenin." (PMID 40149916, 2025). "Another mouse model of colorectal cancer utilizes mutations in the APC gene." (PMID 40624028, 2025). "For example, APC‐deficient colorectal cancer in a mouse model exhibited dysregulation of the methionine cycle due to the upregulated expression of adenosylhomocysteinase (AHCY), and pharmacological inhibition of AHCY effectively reduced intestinal tumor growth in APC‐deficient mice." (PMID 40552664, 2025). "Around 90% of colorectal cancer (CRC) tissues have driver APC mutations." (PMID 41514557, 2025). "Compared to existing molecular tools for colorectal cancer staging—such as APC, KRAS, BRAF, NRAS and PIK3CA mutations—our study offers a novel transcriptomic perspective by identifying stage-specific gene expression signatures that distinguish adenoma, CIS and adenocarcinoma." (PMID 40362431, 2025). "Mutated APC is found in >80% of colorectal cancers, indicating that colorectal cancers may require an alternative therapy." (PMID 40376615, 2025).
colorectal cancer (continued). "The APC (NM_000038.6) c.3920T>A p.Ile1307Lys (I1307K) missense variant has been associated with a moderate/low increased risk of colorectal cancer (CRC) in individuals of Ashkenazi Jewish (AJ) descent, in whom the allele frequency is the highest (minor allele frequency (MAF): 3.7%)." (PMID 40866199, 2025). "Mutations in the tumour suppressor gene APC occur frequently in colorectal cancer." (PMID 40525649, 2025). "In contrast, mutations in the APC are uncommon in the serrated colorectal cancer (SCC) pathway, which is initiated by activating mutations in BRAF or KRAS and usually progresses to malignancy through a plethora of epigenetic alterations, microsatellite instability and MLH1 hypermethylation." (PMID 40357363, 2025). "This proposed mechanism mirrors the well-established multi-step model of familial colorectal polyposis driven by germline mutations in the tumor suppressor gene APC, where an initial germline mutation leads to benign polyposis, and a subsequent somatic mutation causes colorectal cancer." (PMID 40868176, 2025). "The APC c.3920T>A variant doubles the risk of colorectal cancer in individuals of Ashkenazi Jewish descent, although its role in BC risk remains unclear." (PMID 40361347, 2025). "In colorectal cancer, the Wnt signaling transduction cascade is frequently impaired, most commonly through inactivating mutations of the tumor suppressor APC, causing insufficient degradation of β‐catenin and pathologically hyperactive transcription of β‐catenin target genes." (PMID 39022865, 2025). "Notably, APC‐derived mutations were predominantly observed in colorectal cancer (18.6%, 11/59), while TERT promoter and CTNNB1 mutations were most found in liver cancer, with detection rates of 34.5% (10/29) and 24.1% (7/29), respectively." (PMID 39748775, 2025). "Therefore, greater focus should be placed on managing BMI, particularly for those with high risk of colorectal cancer and liver cancer, such as those with APC mutations, inflammatory bowel disease, and cirrhosis." (PMID 40717954, 2025). "APC mutations in colorectal cancer are typically truncating." (PMID 38282550, 2024). "However, the loss of APC function causes a constant activation of β-catenin, contributing to both the initiation and progression of colorectal cancer." (PMID 39766864, 2024). "The interconnection between APC inactivation and aberrant lipid metabolism activates Wnt/beta-catenin signaling which causes transcriptome, epigenetic, and microbiome changes to promote colorectal cancer initiation and progression." (PMID 38590663, 2024). "The high frequency of APC mutations in colorectal cancer raises the question of whether restoring normal APC levels is possible." (PMID 39766864, 2024). "APC is another gene known to be associated with hereditary polyposis and colorectal cancer." (PMID 39684352, 2024). "However, CDX2-suppressed colorectal cancers had a higher prevalence of mutations in alternative genes of the WNT/APC/β-catenin and KRAS/BRAF/MEK pathways." (PMID 39452477, 2024). "Interestingly, it was reported that short-form APC mutations are potential biomarkers of TNKSi sensitivity in colorectal cancer." (PMID 39065798, 2024). "Familial adenomatous polyposis (FAP) accounts for 1% of all colorectal cancer cases and is an autosomal dominant trait with varying expression of the phenotype caused by a disease-causing variant in the adenomatous polyposis coli (APC) gene." (PMID 39493133, 2024).
colorectal cancer (continued). "Interestingly, KRAS mutations are not detected in early colon adenomas, and are instead detected after APC mutations in late adenomas during the development of colorectal carcinomas." (PMID 38474205, 2024). "Indeed, human CRC cases and colorectal cancer cell lines show frequent mutations in the APC gene, resulting in loss-of-function." (PMID 37760541, 2023). "APC mutations were predominantly studied in colorectal cancer." (PMID 38188288, 2023). "Furthermore, tumors without mutations of APC were reported to be carry a worse prognosis than single APC mutation tumors in patients with colorectal cancers." (PMID 37633919, 2023). "Furthermore, both S45P and D32G showed upregulation of Notum, a negative Wnt regulator previously shown to promote cell competition in APC-deficient colorectal cancer cells." (PMID 37591832, 2023). "The prognostic phenotype is heterogeneous in colorectal cancer (CRC) patients with APC mutations, while the diagnostic biomarkers remain largely unknown." (PMID 36934880, 2023). "The contribution of APC variants in colorectal cancer is also well established." (PMID 37277882, 2023). "Finally, another potential therapy option is likely relevant to colorectal cancer patients diagnosed with Familial Adenomatous Polyposis (FAP) who harbour germline APC mutations." (PMID 37048063, 2023). "To date, there are a total of 14 genes that are suspected to cause different subtypes of colorectal cancer, including mutations in adenomatous polyposis coli (APC) leading to a predisposition to familial adenomatous polyposis (FAP) and defects in mismatch repair genes in Lynch Syndrome." (PMID 37284188, 2023). "Here the work shows TFRC is induced by adenomatous polyposis coli (APC) gene loss‐driven β‐catenin activation in colorectal cancer, whereas TFRC‐mediated intratumoral iron accumulation potentiates β‐catenin signaling by directly enhancing the activity of tankyrase." (PMID 36703617, 2023). "WNT signaling is the principal pathway underlying colorectal carcinoma in which APC gene inactivation (5q21) is the initiating event which may be germline (inherited as in FAP) or somatic (acquired)." (PMID 37658412, 2023). "In this study, we investigated the biological functions of a HER2 mutation (G776S mutation) of unknown pathological significance, which was detected together with APC mutation by cancer genome sequencing of samples from a colorectal cancer (CRC) patient." (PMID 35654814, 2022). "Given that the prevalence of APC mutations is shown to be lower in BRAF mutated colorectal cancers, alternative modes of pathway activation are at play and may involve inhibition of kinase GSK3 through PI3K/AKT signaling." (PMID 36079062, 2022). "Colorectal cancer is known to often develop through a specific number of events along the so‐called conventional pathway, which is a multistep process initiated by mutations in APC, KRAS or BRAF genes." (PMID 35383926, 2022). "However, a recent study suggests that colorectal cancer tumors with a single APC mutation can have a survival benefit, whereas tumors lacking any APC mutations convey a worse prognosis." (PMID 35359365, 2022). "Adenomatous polyposis coli (APC) is a highly mutated oncogene in colorectal cancer." (PMID 35844556, 2022). "Frequent mutation of APC (90%) in advanced colorectal cancer (CRC) results in the simultaneous activation of Wnt/β-catenin and AKT signaling pathways, and the current therapeutic limitations of the AKT inhibitors for treating CRC patients are nuclear β-catenin-induced EMT and bypassing apoptosis." (PMID 36547070, 2022). "The situation may be similar in colorectal cancers, where β-catenin activation via APC mutation is common." (PMID 35536676, 2022). "To test this hypothesis, we examined more colorectal cancer cell lines, including 6 other lines carrying mutations of either the APC tumour suppressor gene or the CTNNB1 (β‐catenin) gene." (PMID 35301819, 2022).